LINC02570 (long independently transcribed non-coding RNA 2570)
Synonyms: XXbac-BPG27H4.8
Gene: Long non-coding RNA gene on chromosome 6 (30,838,324 to 30,848,276, reverse strand). Ensembl gene ENSG00000237923.
Diseases named in the same sentence as LINC02570 in open-access papers:
LINC02570 is named in the same sentence as 1 disease in open-access papers, as found by Europe PMC text mining. Sharing a sentence is not in itself a finding about the gene and the disease. The quoted sentences say what the papers report.
tumor (1 paper, 2022). "Although the correlation between LMP1 and LINC02570 has not been reported, LINC02570 shows a new function of ceRNA in the activation of lipogenesis, an effect that accelerates NPC proliferation and tumor development." (PMID 36230487, 2022).